PPARG (peroxisome proliferator activated receptor gamma)
Diseases named in the same sentence as PPARG in open-access papers (continued):
Sharing a sentence is not in itself a finding about the gene and the disease.
tumor (continued). "This may be due to PPARγ-dependent activation of intrinsic oncogenic pathways, such as wnt, or contributions of the tumour stroma responding to a prolonged treatment of TZDs, which may counteract their beneficial effects on cisplatin in the PyMT mice." (PMID 23629957, 2013). "Since NT5E and DCLB2 inversely affect cell proliferation and associate with patients’ outcome, the interplay of TNF-α with PPARγ revealed by our approach could represent a pivotal relay-point in determining tumor progression towards a more aggressive behavior." (PMID 24133572, 2013). "Here, we will focus on how activation of PPARγ in different stromal cells may impact tumor progression." (PMID 22934105, 2012). "Moreover, BADGE has been shown to have PPARγ-independent action on apoptosis in tumor cells, supporting the idea that BADGE can have PPARγ-independent effects." (PMID 22763116, 2012). "In contrast, xenografted mice treated with PPARγ agonists show an increased tumor growth." (PMID 22991505, 2012). "Specifically, PPARG has been shown to protect against tumor progression." (PMID 22848209, 2012). "Arrest in G1 phase through PPARγ activation has been described in different tumor cell lines." (PMID 23213321, 2012). "Ciglitazone, which inhibits proliferation of A549 cells in vitro by a PPARγ-independent mechanism also significantly reduced A549 tumor weights in the nude mouse xenograft model, with concomitant reduction in cyclin D1 and increased expression of the cell cycle inhibitor p21." (PMID 22778711, 2012). "In addition to affecting the biology of the tumor cells themselves, activation of PPARγ also reduced production of the tumor cell-derived cytokines CXCL8, CXCL5, and CXCL1, which are critical for angiogenesis and tumor-stromal interactions." (PMID 22934105, 2012). "Indeed, inhibiting PPARγ was markedly beneficial in counteracting hyperproliferation, reducing tumor burden, and extending the survival of Shh-driven MBs in mice." (PMID 22407012, 2012). "This relatively low PPARγ expression was also found in other tumor cells, and some studies begin to suggest that PPARγ agonists may inhibit cell proliferation in the neoplastic cell lines." (PMID 22448166, 2012). "PPARγ is a candidate tumour suppressor gene and member of the nuclear receptor superfamily." (PMID 22966225, 2012). "Thus, activation of PPARγ in lung and other cancers can lead to either tumor suppressive or promoting responses, based on the set of conditions encountered." (PMID 22934105, 2012). "Thus, as our laboratory has demonstrated, activation of PPARγ in both tumor cells and in cells in the tumor microenvironment by systemic agents will likely have opposing effects on tumor progression." (PMID 22934105, 2012). "Moreover PPARγ suppresses tumor cell growth through reducing cell proliferation and inducing G2/M phase arrest, apoptosis, and upregulating the putative suppressor gene, growth differentiation factor-15." (PMID 22966221, 2012). "In particular, pioglitazone inhibited primary tumor growth in PPARγ-Macneg mice." (PMID 22145026, 2011). "This could be a result of selective effects on tumor cells, but could also involve PPARγ-independent effects." (PMID 22145026, 2011). "However, the role of PPARγ in tumorigenesis is controversial, stemming from the discrepancy between the anticancer effects suggested by in vitro studies, and the tumor-promoting capacity reported in mouse models of colon cancer." (PMID 22194735, 2011). "The demonstration of the PAX8/PPARγ fusion oncogene in a subset of follicular thyroid tumors provides a new and promising starting point to dissect the molecular genetic events involved in the development of this tumor form." (PMID 22654559, 2011). "However, there are several studies which would support a role for PPARγ as a tumor promoter, as our data would suggest, especially in vivo." (PMID 22194735, 2011). "In addition, PPARγ activators have been shown to inhibit tumor initiation in a chemical carcinogenesis model." (PMID 22145026, 2011).
tumor (continued). "Moreover, the amount of phosphorylated, hence inactivated, PPARγ was virtually equal in tumours from RGZ-treated and control mice." (PMID 20068562, 2010). "The reasons behind these paradoxical effects are still unknown and need to be elucidated as it suggests that PPARγ-mediated pathways are likely modulated by specific downstream signaling events in various tumor environments." (PMID 21144036, 2010). "In conclusion, we hope that this paper has provided a conceptual framework upon which future studies will be designed to unravel the pleiotropic effects of PPARγ in the context of the stromal microenvironment during tumor angiogenesis, growth and metastasis in hematological malignancies." (PMID 20204067, 2010). "A group of PPARγ-modulating agents sensitize tumor cells to TRAIL-induced apoptosis." (PMID 20339586, 2010). "Combined together, these suggested a potential crosstalk of PPARγ with Pak signaling in mediating AktSer473 phosphorylation, which might explain the tumor promoting effects of PPARγ activation reported in earlier studies." (PMID 21144036, 2010). "It would be interesting to determine whether these miRNAs suppress PPARγ function during angiogenesis and/or tumor growth." (PMID 20204067, 2010). "One possibility is that PPARγ expression by the tumor may program these cells to be less immunogenic or possibly lead to the secretion of molecules that would end up promoting tumor growth." (PMID 20885923, 2010). "The authors speculate that this PPARγ-independent production of protumorigenic COX-2 may counteract any tumor-suppressing function of PPARγ." (PMID 20508724, 2010). "Several studies have demonstrated that PPARγ agonist, thiazolidinedione, a class of anti-diabetic drugs including rosiglitazone and troglitazone, significantly inhibit primary tumor growth and metastasis in a variety of cancers including colon, breast, prostate, brain and lung." (PMID 20226009, 2010). "Moreover, PPARγ expression is found in tumor cells, where its activation facilitates antitumorigenic actions." (PMID 21057731, 2010). "However, one study disputed the PPARγ agonist role in tumor promotion, as it showed that PPARγ agonists were able to induce differentiation and inhibit human tumors from growing in nude mice." (PMID 20182546, 2010). "Furthermore, these ligands upregulated EC expression of PPARγ and CD36, which likely leads to the synergistic inhibition of tumor-associated angiogenesis and induction of EC apoptosis in vivo." (PMID 20204067, 2010). "Moreover, pretreatment of rosiglitazone with cisplatin showed maximum increase in PPARγ expression which was well correlated with maximum percentage of tumour inhibition." (PMID 19356226, 2009). "Although the mouse MnSOD gene has been shown to be a PPARγ target gene, a direct association between PPARγ and human MnSOD from tumor cells' perspective has not been shown." (PMID 19958503, 2009). "By immunohistochemical analysis of primary tumors, PPARγ was often found in low-grade tumors, especially in tumor endothelium, and a favorable impact of PPARγ expression on relapse-free survival of the patients could be demonstrated." (PMID 19794826, 2009). "Therefore, we conclude that PPARD's activation on DVL1 leads to repressing PPARG's activity, and this gives clues for tumour repressor PPARG's inactivation and leads to cancer progression into the HR stage." (PMID 19640296, 2009). "Genetic causes have been excluded since neither mutations in PPARG gene nor deletions in chromosomal region were detected in prostate cell lines or in tumours." (PMID 19640296, 2009). "All these studies have suggested that PPARγ functions as a tumor-suppressor gene and it might be involved in cancer suppression under the physiological conditions." (PMID 19884989, 2009). "These genetic evidences support the hypothesis that PPARγ serves as tumor suppressor incolorectal cancer." (PMID 18551185, 2008).
tumor (continued). "Moreover, apart from their direct inhibitoryeffects on cancerous transformed cells, PPARγ can also inhibit angiogenesiswhich is a prerequisite for tumor formation and growth." (PMID 18779870, 2008). "Moreover, PPARγ exhibits antiangiogenic effects byinhibiting VEGF expression in tumor cells and VEGF receptors in endothelialcells." (PMID 18551185, 2008). "The anticancer effects of PPARγ agonists may also be mediated in part viasuppression of an angiogenic tumor phenotype or angiogenic, inflammatory tumormicroenvironment." (PMID 19125177, 2008). "PPAR-γ activation antitumor effects by ligands appear to be mediated by means of both PPARγ-dependent and -independent (off-target) pathways, depending on agonist type, concentration, and tumor cell type." (PMID 18947424, 2008). "However, PPARγ and its ligands exhibit a janus-face behaviour as tumor modulators in various systems, resulting in either tumor suppression or tumor promotion." (PMID 18596912, 2008). "Experiments in rodents have shownincreased frequency and enhanced tumor growth by PPARγ agonists." (PMID 18551186, 2008). "Thus, a novel pathwaylinking n-3 PUFAs to apoptosis in tumor cells is as follows: DHA activates PPARγ, which results in transcriptionalupregulation of the syndecan-1 target gene, and the syndecan-1 protein inducesapoptosis." (PMID 18769551, 2008). "To this regard, we tend to speculate thatalternative locations of PPARγ in the cell may determine the balance between tumor-suppressive and tumor-promotingfunctions." (PMID 18596912, 2008). "In addition, theability of PPARγ to suppress tumor growth is also through inhibiting APC/β-catenin andCOX-2/PGE2 signaling pathways, which are pivotally involved in coloncarcinogenesis." (PMID 18551185, 2008). "Induction ofPPARγ by 15-LOX metabolites and by COX-2 inhibitors and PPARγ effects on COX-2activity, among other results, are pointing out a cross-talk betweeneffectors of the AA pathway (LOX and COX products) and PPARγ activity.Deregulation of this cross-talk is thought to allow tumor progression." (PMID 19277204, 2008). "In sum, these studiesinitially corroborated the role of PPARγ as a tumor suppressor, which may be shut down byMAPK-phosphorylation." (PMID 18596912, 2008). "Thus, the use of PPARγ modulators to manage tumor progressionis more complex than itappears at a glance and requires precise knowledge of the molecular eventsinvolved in their pro- and antitumorigenic actions." (PMID 19043603, 2008). "According to these observations, we cannot discard the fact that in vivo, the inflammatory tumor microenvironment (macrophages, lymphocytes, endothelial cells) might regulate PPARγ expression in tumor cells." (PMID 18261208, 2008). "In addition to TZD drugs,also the physiological eicosanoid-type ligands for PPARγ exert tumor-modulating effectsthrough their ability to trigger ERK cascade activation." (PMID 18596912, 2008). "If suppression of PPARγ cannot be separated from the tubulin targeting effects, it will benecessary to carefully balance the therapeutic effects of PPARγ inhibitors ontubulin with the possible deleterious effects of PPARγ inhibition onphysiologic processes that affect tumor growth." (PMID 18509498, 2008). "Theseparadoxical observations appear to have been resolved by genetic studiesshowing that the heterozygous disruption of PPARγ is sufficient to increase tumor numberin AOM-treated mice and that intestinal-specific PPARγ knockout promotes tumor growthin ApcMin/+ mice." (PMID 18551185, 2008). "Upregulation of PPARγ hasbeen demonstrated during tumor progression." (PMID 18784849, 2008). "Finally, throughdisruption of tumor-stromal communication via inhibition of chemokineproduction, PPARγ can negatively impact tumor progression and metastasis." (PMID 18509496, 2008).
tumor (continued). "In addition, T0070907causes cell death at concentrations far lower than those needed for PPARγ agonists rosiglitazone and troglitazone.Together, the data suggest that PPARγ functions to promote tumor cell adhesion andsurvival in HCC cells." (PMID 18784849, 2008). "Although the COX-2promoter contains multiple regulatory elements, their data indicatethat the inhibitory effects of PPARγ are mediated through NF-κB.Several studies have demonstrated that constitutive activation ofNF-κB in tumor cells is mediated through activation of Akt." (PMID 18769553, 2008). "Since PPARγ activation of humanmonocytes promotes M2 polarization, PPARγinhibitors might be expected to favor production of M1 tumor-suppressinginflammatory macrophages." (PMID 18509498, 2008). "Studies on the expression of PPARγ in LMM3 tumor cells showed that RGZ augmented its expression." (PMID 18261208, 2008). "In all probability, the net effect of PPARγ inhibition on the immunesystem will depend upon the individual characteristics of the tumor, including thesite of the tumor, the role of PPARγ in tumor-intrinsic biology, and thepresence and type of immune infiltration." (PMID 18509498, 2008). "Similarly, in 22 patients with nonsmallcell lung carcinoma, higher levels of PPARγ areexpressed in tumor cells than in the surrounding normal tissue, as determinedby immunohistochemical staining." (PMID 18784849, 2008). "Thus, this review will specificallyfocus on the role of PPARγ and its ligands in regulation of tumor cellapoptosis." (PMID 18615184, 2008). "PPARγ pro-angiogenic effects are associatedwith the induction of VEGF and increased phosphorylation of eNOS and AKT, which cause elevated VEGFproduction in human and rodent VSMCs, MΦs and tumor cells, VEGF and VEGFR levels in theECs and myofibroblasts." (PMID 19043603, 2008). "Watchfor spontaneous tumor formation in certain PPARγ genetic backgrounds has also been conducted." (PMID 18784849, 2008). "Indeed, several in vivo studies have demonstrated that genetic alterations of PPARγ can promote tumor progression." (PMID 19096712, 2008). "However, activation of PPARγ under these circumstances had a profoundinhibitory effect on tumor progression." (PMID 18615192, 2008). "A large body of evidence indicates that PPARγ serves as a tumor suppressor." (PMID 18551185, 2008). "Recent data have also suggested that PPARγ anti-tumor activity required a functional RARβ." (PMID 17767717, 2007). "RXR may also exert its effects on tumor cell survival and growth by partnering with PPARγ and/or NR4A1." (PMID 17407572, 2007). "Interestingly, recent studies found that PPARγ ligands can upregulate PTEN expression by enhancing PPARγ transcriptional activity in several types of tumor cell lines." (PMID 18021457, 2007). "As for PPARγ, the integrity of the tumor suppressor APC might be essential to guarantee PPARδ normal function." (PMID 17767717, 2007). "Indeed, the antiproliferative activity of PPARγ is now investigated to limit and treat tumour cell proliferation although several PPARγ ligand-mediated antiproliferative effects act through a complexity of PPARγ-independent mechanisms." (PMID 17710234, 2007). "These and related studies support a role for PPARγ as a potential tumor suppressor." (PMID 17597835, 2007). "The presence in the tumour tissue of a transcriptionally active PPARγ might for instance be useful to select those patients, for whom TZDs might be beneficial." (PMID 16969347, 2006). "In another study, loss of PPARγ was shown not to affect mammary development and propensity for tumour formation but resulted in reduced fertility." (PMID 15583697, 2005). "Furthermore, it has been reported that differentiation and reversal of malignant changes were induced in CX-1 colonic tumour cells treated with PPARγ agonist in Swiss nude mice." (PMID 15266333, 2004).
tumor (continued). "The role of PPARγ in the acquisition of an adipocyte phenotype, through the control of the expression of genes that promote cell cycle withdrawal, drive differentiation and induce apoptosis, prompted many investigators to study the potential function of PPARγ in neoplasia." (PMID 12454768, 2002). "This indicates that the elevated PPARG signal detected in high-risk patients could predominantly originate from the infiltrating stromal compartment rather than the tumor cells." (PMID 41596281, 2026). "Indeed, several studies have demonstrated that the long-term administration of PPARγ agonists or related pharmacologic approaches could suppress tumor progression in different contexts." (PMID 41614948, 2026). "Therefore, it appears conceivable that the PPARγ signal may exert an essential role in designating the action of MDSCs in the tumor immune microenvironment." (PMID 41614948, 2026). "Additionally, PPARγ activation may exert pro-tumorigenic effects within the tumor microenvironment, particularly through modulation of myeloid cells." (PMID 41476922, 2025). "In addition, PPARG expression enhances immunosuppression and modulates the tumour microenvironment." (PMID 40446016, 2025). "However, at low doses, linoleic acid may inhibit tumor progression and promote apoptosis by activating anti-inflammatory pathways such as PPARγ." (PMID 40696666, 2025). "Notably, in TNBC, PPARγ may be co‐opted to fuel tumor progression, underscoring the subtype‐specific metabolic rewiring that is the focus of this study." (PMID 41236441, 2025). "This review examines the dual functions of PPARγ in cancer cachexia, focusing on its regulation of adipose tissue remodeling (including browning and lipid metabolism), skeletal muscle homeostasis, and systemic inflammation, alongside tumor-promoting mechanisms that complicate its therapeutic use." (PMID 41476922, 2025). "Therefore, it is likely that higher expression of genes that promote oxidative metabolism, such as PPARγ, may be protective against tumor progression." (PMID 41236441, 2025). "Conversely, PPARγ agonists may enhance tumor growth in certain cancers, raising safety concerns." (PMID 41476922, 2025). "Additionally, HT increased peroxisome proliferator-activated receptor gamma (PPARγ) expression, which may contribute to its tumor-reducing effects." (PMID 40002421, 2025). "Activating PPAR gamma (PPARγ) could promote the storage of fatty acids and the formation of lipid droplets, which contributes to energy storage and biofilm synthesis in tumor cells, and thus promotes or inhibits tumor growth." (PMID 41364140, 2025). "Furthermore, we discovered that PPARG amplifies osteoclast activation and proliferation, resulting in excessive bone resorption and degradation of the bone matrix, thereby creating a favorable environment for tumor cell proliferation and growth." (PMID 39936154, 2024). "Herein, we summarized the molecular mechanisms of action of agonists and the complex signaling networks resulting from PPARγ activation, which may contribute to the design of PPARγ agonists characterized by more efficient, safer, and potent anti-tumor effects in the future." (PMID 38397426, 2024). "Since POM121 is frequently overexpressed in cancers including CRC, this post-translational inhibition of PPARγ may prevent its anti-proliferative, differentiation-promoting effects in tumor cells and also mitigate its modulatory function on metabolism and immunity." (PMID 38177114, 2024). "Therefore, it is essential to evaluate the systemic effects of PPARγ agonists in tumor sites." (PMID 38397426, 2024).